C11orf40 (chromosome 11 putative open reading frame 40)
Synonyms: NOV1
Gene: Long non-coding RNA gene on chromosome 11 (4,571,423 to 4,577,820, reverse strand). Ensembl gene ENSG00000171987.
Diseases named in the same sentence as C11orf40 in open-access papers:
C11orf40 is named in the same sentence as 2 diseases in open-access papers, as found by Europe PMC text mining. Sharing a sentence is not in itself a finding about the gene and the disease. The quoted sentences say what the papers report.
fibromyalgia syndrome (1 paper, 2023). "Several mutations in C11orf40 were reported previously in patients with fibromyalgia syndrome, but the gene function is not clearly known." (PMID 37895268, 2023).
C11orf40 also shares sentences with these, for which no sentence is quoted: malaria (1 paper).